CDK9 (cyclin dependent kinase 9)
Diseases named in the same sentence as CDK9 in open-access papers (continued):
Sharing a sentence is not in itself a finding about the gene and the disease.
infection (25 papers, 2011 to 2025). The state of being infected such as from the introduction of a foreign agent such as serum, vaccine, antigenic substance or organism. "The interaction of ICP22 and CDK9 causing reduced transcriptional elongation rates of cellular mRNA has been proposed to benefit HSV as a means of countering host responses during infection." (PMID 39316591, 2024). "A direct role of CDK9 on γ2 late gene expression was then demonstrated by an experiment in which addition of DRB 7 h post-infection caused a drastic and specific inhibition of synthesis of HSV-1 late proteins." (PMID 28743741, 2017). "ICP22 is responsible for loss of Ser2 early during infection through its physical association and inhibition of cyclin-dependent kinase 9 (CDK9), which phosphorylates the CTD at Ser2 to promote elongation." (PMID 27092522, 2016). "Much research on ICP22 has focused on its role in altering the CDK9-mediated phosphorylation of the C-terminal domain (CTD) of the RPB1 subunit of Pol II at Ser 2 during infection." (PMID 38399666, 2024). "As previously shown in various models of injury and infection in vivo, we found that CDK9 inhibitors enhance the resolution of neutrophilic inflammation following heart injury in larval zebrafish." (PMID 34523672, 2022). "We stimulated CD4+ T cells from three different donors with equimolar concentrations of IL-2 and IL-15 and analyzed the expression of CDK9 and cyclin T1 after 8 to 9 days of stimulation, a time when latent and productive infection with HIV-GKO was measured." (PMID 35499323, 2022). "CDK9 inhibition dampened pro-inflammatory gene production in the acute infection process in the subcutaneous chamber model in vivo." (PMID 31758083, 2019). "When we compared the H5N1 virus to the seasonal H1N1 virus, the TF CDK9 exhibited high repressive effects from 0 to 12 h post-infection, coincident with overall repression of inflammatory TFs." (PMID 27131787, 2016). "Knock-out of each P-TEFb component (CCNT1, CDK9) significantly decreased infection." (PMID 39259751, 2024). "Because transcription disturbs chromatin stability, we used the CDK9 inhibitor flavopiridol to inhibit transcription during infection to determine which H3 chaperones might be responsible for de novo H3 deposition rather than maintenance." (PMID 33909709, 2021). "Future study using conditional genetic knockout mouse may provide more information about CDK9-mediated transcription modulation in the infection." (PMID 31758083, 2019). "To corroborate this conclusion, we first determined whether Ad infection required CDK9 activity by treating the cells with CDK9 inhibitors 1 h prior to infection." (PMID 30068949, 2018). "Moreover, CDK9 targeted the majority of TFs predicted to be highly activated (average Enrichment Score of >10) in the late phase of infection (after 8 h post infection)." (PMID 27131787, 2016). "Finally, we determined CDK9 and cyclin T1 expression, as well as NF-κB localization, at the time when we analyzed the outcome of infection; we cannot exclude that earlier time points might be relevant as well." (PMID 35499323, 2022). "This may reflect differences in ICP22 action when it is ectopically expressed in cells on its own in our experiments and ICP22 action in the context of infection, differences in the effect on host cell and viral genes or that ICP22 has different effects on CDK9 and Cyclin T1 association." (PMID 25233083, 2014). "Knockout of CXCR4 (green dots), resulted in strong decreases in infection rates at all three timepoints, as did knock out of LEDGF and CDK9." (PMID 35365639, 2022). "Concurrently, we showed that CDK9 inhibition blocked Ad infection and JQ1 enhancement on the infection." (PMID 30068949, 2018). "The expression of Bombyx mori SPT5 (BmSPT5) and Bombyx mori NELF-D (BmNELF-D), but not Bombyx mori CDK9 (BmCDK9), were upregulated after BmNPV infection." (PMID 36560640, 2022).
infection (continued). "Since, CDK9 plays a crucial role in HIV-1 Tat protein mediated transactivation, a possible role of increased Tat function in the productive infection may also be considered likely." (PMID 21226936, 2011). "When bacterial invasion activates intracellular NF-κB/MAPK signaling pathways, CDK9 is rapidly recruited to the promoter regions of immune genes, initiating the transcription of TNF-α, IL-6, and IL-1β genes and guiding immune cell migration to the infection site." (PMID 41515060, 2025). "Others have observed a rapid loss of RNA Pol II Ser-2 phosphorylation when ICP22 is expressed in cells either transiently or at later times during infection, indicating that Ser-2 phosphorylation by cdk9 may not be necessary for efficient viral transcription." (PMID 28611249, 2017).
hematologic cancer (10 papers, 2018 to 2025). "The CDK9 inhibitor AZD4573 is the first CDK9-selective inhibitor and has entered clinical trials for hematological cancers." (PMID 35567477, 2022). "A structure-based approach led to the identification of AZD4573, a highly potent CDK9 inhibitor with over 25-fold selectivity for CDK9 over other CDKs, and broad antitumor activity across preclinical hematologic cancer models." (PMID 35568739, 2022). "This review provides a comprehensive discussion on the structure and biology of CDK9, its role in solid and hematological cancers, and an updated review of the available inhibitors currently being investigated in preclinical and clinical settings." (PMID 34041038, 2021). "Next, we tested the combination of BTYNB with AZD4573, a highly selective CDK9 inhibitor that has been shown to arrest cell proliferation and induce apoptosis in hematologic cancers." (PMID 33796454, 2021). "CDK9 inhibitors have been investigated as therapeutics for a variety of hematologic cancers and solid tumors." (PMID 29471852, 2018). "Previous studies revealed that CDK9 inhibitors induce apoptotic cell death, reducing the expression level of MCL1 in hematological cancers." (PMID 40713627, 2025).
adenocarcinoma (2 papers, 2017 to 2024). A common cancer characterized by the presence of malignant glandular cells. "Interestingly, CDK9 mRNA levels were significantly higher in castration-resistant neuroendocrine prostate cancer (NEPC) tumors, which exhibit AR-low/null/independent phenotypes, compared to the more common CRPC adenocarcinoma phenotype." (PMID 39117800, 2024).
bacterial infection (1 paper, 2019). "In conclusion, by modulating the RIPK3-MLKL-mediated necroptosis, CDK9 inhibition provided a novel mechanism to impact the progress of bacterial infection in the periodontal milieu." (PMID 31758083, 2019). "CDK9 inhibition by FVD significantly reduced the level of lactate dehydrogenase (LDH), which indicates the onset of cell death, in both THP-1 monocytes and PBMCs at 4 and 8 hours after bacterial infection, indicating that CDK9 activation may trigger cell death in monocytes." (PMID 31758083, 2019). "In our present study, CDK9 inhibition or knock-down significantly reduced RIPK1, RIPK3 and TRIF levels after bacterial stimulation, thereby may reduce necroptosis during bacterial infection." (PMID 31758083, 2019).
blood cancer (1 paper, 2024). "This genomic data accords with recent studies that demonstrate widespread RNAPII promoter pausing induced in cell line models of blood cancer upon treatment with different CDK9 inhibitors." (PMID 38001268, 2024).
eye disorder (1 paper, 2026). A non-neoplastic or neoplastic disorder that affects the eye. "In this study, we report that a novel compound heterozygous combination of CDK9 missense variants [p.(A288T/P321S)] are associated with human eye disease in the absence of a multiple malformation syndrome." (PMID 40954203, 2026).
neoplastic disorders (1 paper, 2021). "Overall, a holistic understanding of the underlying CDK9 biology will be a prerequisite to optimizing the use of novel kinase inhibitors as mono and/or adjuvant therapies for the future treatment of various neoplastic disorders." (PMID 34041038, 2021).
neurodegenerative disease (1 paper, 2014). A disorder of the central nervous system characterized by gradual and progressive loss of neural tissue and neurologic function. "Especially that is relevant for CDK5, which is involved in neurodegenerative diseases and CDK9, involved in viral replication." (PMID 25349887, 2014).
neurological disorders (1 paper, 2022). "However, roscovitine can also inhibit Cdk1, Cdk2, Cdk7, and Cdk9, the low selectivity for Cdk5 reduces its potential as a drug candidate targeting neurological disorders." (PMID 36438186, 2022).
CDK9 also shares sentences with these, for which no sentence is quoted: endometrial cancer (7 papers); small cell lung carcinoma (4); synovial sarcoma (3); adult T cell leukemia (2); B-cell acute lymphoblastic leukemia (2); Barrett esophagus (2); Hepatitis (2); Hodgkins lymphoma (2); soft tissue sarcoma (2); Ureteral obstruction (2); acute respiratory distress syndrome (1); adenoid cystic carcinoma (1); anaplastic astrocytoma (1); and Muscular Disorder (1); Anxiety (1); ataxia telangiectasia (1); Atherosclerotic lesion (1); B-Cell Acute Lymphocytic Leukemia (1); basal cell carcinoma (1); brain ischemia (1); cardiovascular diseases (1); cerebral malaria (1); choanal atresia (1); chondroblastoma (1); chronic periodontitis (1); clear cell renal carcinoma (1); CNS tumors (1); diabetes (1); esophageal cancer (1); eye coloboma (1).
A further 48 diseases each share a sentence with CDK9 in 1 paper.